PRDX2 (peroxiredoxin 2)
Diseases named in the same sentence as PRDX2 in open-access papers (continued):
Sharing a sentence is not in itself a finding about the gene and the disease.
cancer (continued). "Even though PRDX2 upregulation can be a potential biomarker in various cancers how it is upregulated and its role in OSCC development remains obscure." (PMID 33332365, 2020). "We assessed the relative levels of Prdx2 in the two cancer cell lines and show that BGC-823 cells express higher levels of Prdx2 compared to SGC-7901." (PMID 32929349, 2020). "We note that the level of PRDX2 expression in these OSCC categories was significantly higher than among cancer-free controls." (PMID 33332365, 2020). "Our study provided further evidence in support of the tumor-promoting role of PRDX2 in cancer progression." (PMID 32337219, 2020). "Recent studies identify aberrant expression of PRDX2 in several types of cancers and demonstrate that PRDX2 exerts an important role in cell proliferation, death, and drug sensitivity of cancer." (PMID 32337219, 2020). "Peroxiredoxin 2 (PRDX2), a member of the peroxiredoxin family of antioxidant enzymes, has been revealed to be an important player in cancer progression." (PMID 32337219, 2020). "PRDX2 and PRDX6 encoding peroxiredoxins were reported to be associated with chemoresistance in cancer." (PMID 30925767, 2019). "Together these results suggest that a threshold for ANXA2 depletion is required to trigger PRDX2 up-regulation in cancer cells." (PMID 30959964, 2019). "This enzyme influences several cellular processes involving proliferation, survival, and apoptosis, which suggests a possible role for Prdx2 in the maintenance of cancer cell." (PMID 31100862, 2019). "Here the authors develop a peroxiredoxin-2-based FRET probe that is sensitive enough to measure changes in H2O2 concentration in response to the cancer therapeutic piperlongumine." (PMID 30087344, 2018). "Particularly, transforming growth factor-beta-induced protein ig-h3 (Beta ig-h3) and peroxiredoxin-2 (PRDX2) overexpression in the secretome of cancer cell lines was detected and confirmed by Western blot." (PMID 28261610, 2017). "As the hyperproliferative property of tumor cells is closely related to the increased production of intracellular ROS, Thus, the increased expression of PRDX2, as a scavenger of ROS in cancer cells, is beneficial for the survival and growth of tumor cell." (PMID 28125800, 2017). "Among the proteins that were found to be upregulated in the cancer cell line secretome, transforming growth factor-beta-induced protein ig-h3 (beta ig-h3) and peroxiredoxin-2 (PRDX2) were the focal points of our study." (PMID 28261610, 2017). "Considering the multiple effects of PRDX2 in carcinoma pathobiology, its prognostic implication in malignant diseases has triggered widespread attention." (PMID 28125800, 2017). "The MSigDB Cancer Neighborhood highlighted cancer-associated genes, TAL1, ANK1, SPTB, SPTA1, PRDX2, MAP2K3, etc.." (PMID 25522020, 2014). "Peroxiredoxin-2 and peroxiredoxin-4 in cluster 2, which were up-regulated in many cancers, showed a significant decrease upon OT-treatment for 12 hr but increased to almost basal level after OT treatment for 48 hr." (PMID 23890079, 2013). "When overexpressed, PRDX2 protects cancer cells from oxidative stress and thus mediates resistance to chemo- and radiotherapy." (PMID 21119665, 2011). "Two SL cancer-related partners of PRDX2, RAD50 and MRE11A are part of MRN protein-complex involved in DNA double-strand break repair, cell-cycle checkpoint activation, telomere maintenance and meiotic recombination." (PMID 20015360, 2009). "Prdx2 is involved in metabolic liver disease progressing to cancer in vivo." (PMID 40932790, 2025). "Our study also indicates that the role of PRDX2 in hepatocytes and cancer cells is different." (PMID 40932790, 2025). "Analysis of tissues from patients with HCC confirmed a perturbed expression of PRDX2 in cancer." (PMID 40932790, 2025). "Given that PRDX2 is associated with lower survival rates in patients with TNBC and cancer recurrence, PRDX2 could be a meaningful biomarker for the early detection of MDSC‐dominant BRCA." (PMID 39939411, 2025).
cancer (continued). "High amounts of PRDX1 and/or PRDX2 and their growth-supporting functions have been documented in several cancer types, suggesting that inhibitors of these enzymes may exert anticancer activity." (PMID 37566013, 2023). "Several studies have confirmed the oncogenic role of PRDX2 in different types of cancer." (PMID 38188679, 2023). "CLT exerts its antitumor effect in various ways, including increasing reactive oxygen species (ROS) levels and causing ROS-dependent endoplasmic reticulum (ER) stress, mitochondrial dysfunction, and apoptosis by inhibiting peroxiredoxin-2 (PRDX2, an antioxidant enzyme in cancer cells)." (PMID 36670444, 2023). "In particular, the tumor-promoting effect of PRDX2 is well established in several cancers." (PMID 33819194, 2021). "Interestingly, QGP-1 spheroid cells, which exhibited cancer stem cell-like features in vitro and in a xenograft model, expressed low levels of Prdx2 and exhibited low activation of mTOR-related signaling pathways." (PMID 33182509, 2020). "PRDX2, as one member of Peroxiredoxins family, has been found to be highly expressed in different tumors and exerts the effects on the regulation of occurrence and development of cancers." (PMID 32908916, 2020). "Emerging evidences reveal that PRDX2 functions a protumorigenic role in cancer progression." (PMID 32337219, 2020). "PRDX2 is upregulated (and therefore could be a biomarker) in various cancers including colorectal, renal, breast and lung cancers." (PMID 33332365, 2020). "Interestingly, QGP-1 spheroid cells, which exhibited cancer stem cell-like features, exhibited lower expression of Prdx2 and mTOR." (PMID 33182509, 2020). "In summary, we observed increased expression of PRDX2 upon depletion of ANXA2 in cancer cells." (PMID 30959964, 2019). "In addition, over-expression of PRDX2 has been reported in various cancer tissues and cells, which is essential for tumor maintenance and survival by protecting cells against ROS injury and apoptosis." (PMID 28125800, 2017). "All cancer cell lines expressed high levels of PRDX2 protein compared with the HCEC." (PMID 28125800, 2017). "Moreover, several studies have reported down-regulation of PRDX2 expression had a good therapeutic effect for cancer." (PMID 28125800, 2017). "Furthermore, PRDX2 localized to the nucleus and PRDX2 depletion markedly promoted cell death in cancer cells treated with DNA damaging agents." (PMID 28432271, 2017). "Moreover, downregulation of PRDX2 sensitizes some cancer cells to radiation and chemotherapeutic drugs." (PMID 26133262, 2015). "However, elevated levels of each Prdx family member have been found in a variety of cancer cell lines and tissues and Prdx2 can directly suppress the activity of several pro-apoptotic factors." (PMID 24019887, 2013). "However, peroxiredoxin-2 and peroxiredoxin-4 of cluster 2, the same ubiquitous family of peroxiredoxin-6, which were up-regulated in many cancers, were shown in an upright “V” shape." (PMID 23890079, 2013). "There is evidence suggesting that PRDX2 may have a proliferative effect and play important roles in cancer development or progression as well." (PMID 22815861, 2012). "N-carbamoyl alanine and 3-sulfinoalanine compounds were found to be inhibitors of PRDX2 activity and it has not been yet associated to any anti-cancer treatment." (PMID 20015360, 2009). "Therefore, the final detectable amount of PRDX2 in tumors may depend on the net effect of the presence of non-cancer cells infiltrating the tumor." (PMID 36604669, 2023). "However, the biological functions of PRDX2 in cancer have not been completely understood." (PMID 34117220, 2021).
cancer (continued). "Therefore, Prdx2 may play different roles according to cancer type and our data provide insight into the role of Prdx2 in pNEN." (PMID 33182509, 2020). "Hence, Prdx2 is a key regulator of prognosis and treatment resistance in a variety of cancers." (PMID 33182509, 2020). "In this context, we propose four potential biomarkers, SPP1, LTF, CARL, and PRDX2, for the early detection of MDSC‐dominant cancer." (PMID 39939411, 2025). "Collectively, OSCC cancer cells can upregulate RUNX2 isoform II to inhibit ferroptosis and apoptosis and facilitate tumorigenesis through the novel HOXA10/RUNX2 isoform II/PRDX2 pathway." (PMID 40498062, 2025). "Given that peroxiredoxin 2 (PRDX2) reduces ROS production and contributes to anti-apoptotic mechanisms in cancer cells, molecular docking techniques suggest that triptolide binds to PRDX2 at the Cys172 site, directly hindering PRDX2’s function." (PMID 39770441, 2024). "The second subnetwork containing 13 nodes and 12 edges showed the interaction between PRDX2 and TAGLN2 as well as a mild increase in multiple components of the peroxisome (SOD1, CAT, PRDX5, PRDX1) and proteoglycans in cancer (FLNA, STAT3)." (PMID 38322285, 2023). "Several studies have also proved the involvement of PRDX2 in HCC progression, making it a valuable candidate for assessing therapeutic efficacy and cancer prognosis." (PMID 38188679, 2023). "We further investigated the overexpression of PRDX2 in COAD and found that PRDX2 expression was high across multiple tumor histological subtypes, cancer nodal metastasis status and individual cancer stages." (PMID 32692719, 2020). "To further unravel the mechanism of PRDX2 in CRC, we investigated gene expression profiles in The Cancer Genome Atlas (TCGA) through the UALCAN cancer database." (PMID 32692719, 2020). "Peroxiredoxin-2 (PRDX2), an important member of peroxiredoxin family, has been reported to be aberrant expression in various cancers and exerts dual roles in cancer progression." (PMID 29258530, 2017). "Overexpression of PRDX2 and PRDX3 has been reported in many kinds of cancer though it’s low or even undetectable in normal tissues." (PMID 28184180, 2017). "It will be interesting to determine if PRDX2 and PRDX4 regulate the aggressive phenotype of cancer cells under prolonged hypoxia." (PMID 26837221, 2016). "In our previous study, we found that the radioresistant cancer cells are more tolerant than control cells to irradiation owing to the modulation of cellular antioxidant defense proteins such as Mn-SOD, PRDX2, and CLIC1." (PMID 25605256, 2015). "We found, for instance, that 6 cancer-related targets changed their expression levels: HSPD1, PARP1, XRCC5, PRDX2, MTA2 and FASN." (PMID 24801752, 2014). "Finally, thiostrepton induced cancer cell death in multicellular patient-derived tumor spheroids generated from authentic HCC tumors, confirming that PRDX2 plays a role in apoptosis resistance in HCC." (PMID 40932790, 2025). "MS17 induced the upregulation of PRDX2 and TKT with the TALDO1 downregulation in SW620 cells, which may interfere with the cancer metabolism and increase ROS production to induce cellular stresses, leading to apoptosis." (PMID 38542474, 2024). "Levels of PRDX1 and PRDX2 protein were estimated in the urine of 100 cancer patients and 50 non-malignant controls by ELISA." (PMID 35812179, 2022). "Thus far, only peroxiredoxin-2 was reported to promote MAP kinase-driven autophagy, fostering thereby cancer cell proliferation." (PMID 33805811, 2021). "Protein levels of Prdx2, measured by immunoblotting and tissue staining, also showed increased levels in cancer specimens compared to non-tumoral tissue." (PMID 32929349, 2020). "Many nutraceuticals and antioxidants, such as vitamin C, selenium, and lycopene, have been developed for cancer prevention and treatment as they can scavenge ROS; likewise, AZA can exert antileukemic effects by decreasing ROS levels via upregulation of Prdx2 and Prdx3." (PMID 33425206, 2020).
cancer (continued). "Additionally, 11 step-changing proteins (including KRT families, PRDX2, CALD1, and others) were decreased in the IBC tissues compared with both cancer-adjacent and normal." (PMID 33194682, 2020). "Thus, our results based on functional network analysis and thus a predictive bioinformatic model could indicate that PRDX2, LCP1, OGN and TAGLN2 might impact the IPF progression through mechanisms common to cancer." (PMID 38322285, 2023). "Furthermore, genetic targeting of PRDX1 or adenanthin, but not PRDX2, potently sensitised all six cancer cell lines studied, but not the non-cancerous cells, to glucose oxidase and ascorbate." (PMID 30287919, 2018). "Six proteins 60Sacidic ribosomal protein P2, Peroxiredoxin-2, Annexin A5, PDZ and LIM domain protein 1, Src substrate cortactin and Moesin were found as emerging proteins of the H22 cell incubated with high dose lentinan which related to cancer promotion closely." (PMID 29221118, 2017). "The mRNA levels of three out of six genes we tested (SLC2A3, GPI, and PDK3) were selectively decreased by PRDX2 and PRDX4 during prolonged hypoxia, suggesting that PRDX2 and PRDX4 may be negative regulators of glucose reprogramming in cancer cells exposed to prolonged hypoxia." (PMID 26837221, 2016). "Interestingly, when we depleted PRDX2 in cancer cells we did not observe up-regulation of ANXA2." (PMID 30959964, 2019). "Second, the efficacy of Prdx2 overexpression in QGP-1 spheroid cells was not validated and the relationship between Prdx2 expression and cancer stem cell proliferation was not confirmed." (PMID 33182509, 2020). "However, no significant expressional difference of PRDX2 was shown between the colonospheres and their parental HT29 cancer cells." (PMID 32231717, 2020). "In contrast, depletion of PRDX2 by shRNA did not lead to up-regulation of ANXA2 in either MDA-MB-231, MCF7 or HCT-116 cancer cells.To investigate if the up-regulation of PRDX2 in HT1080 ANXA2 KO cells was regulated by ROS, we treated these cells with the antioxidant N-acetyl cysteine (NAC)." (PMID 30959964, 2019). "The authors also show that PRDX2 was not able to bind to PTEN, which is in agreement with our results, demonstrating that PRDX2 up-regulation is not able to impede the enhanced AKT phosphorylation observed upon depletion of ANXA2 in cancer cells." (PMID 30959964, 2019).
tumor (71 papers, 2008 to 2026). "By contrast, PRDX2 overexpression showed only modest effects on OS and was associated with reduced immune signalling and diminished infiltration of anti-tumor immune cells." (PMID 41761027, 2026). "The high expression of PRDX2 is reported to be associated with increased resistance to chemotherapeutic drugs and associated with a high proliferation rate and tumor recurrence 12,13." (PMID 35812179, 2022). "In our research, we revealed decreased PRDX2 mRNA expression was significantly associated with unfavourable OS in GC patients, suggesting the tumor suppressor role of PRDX2 in GC." (PMID 32382548, 2020). "We also revealed a regulatory loop by which the loss of PRDX2 inhibits tumor metastasis and chemotherapeutic resistance." (PMID 32692719, 2020). "Increased expression of PRDX2 protein was significantly associated with poor tumor differentiation (p = 0.001), advanced local invasion (p = 0.046), increased lymph node metastasis (p = 0.008), and advanced TNM stage (p = 0.020)." (PMID 28125800, 2017). "Since tumor chemotherapeutic resistance is associated with metastasis, we assessed contribution of the c-Myc/miR-200b-3p/PRDX2 regulatory loop to chemotherapeutic resistance of CRC cells." (PMID 29258530, 2017). "A number of recent studies have shown that PRDX2 is involved in tumor proliferation and differentiation, associated with signaling pathways within apoptotic cells." (PMID 29207610, 2017). "Next, based on the widely recognized view that CSCs are responsible for tumor metastasis, we assessed whether PRDX2 is functionally associated with the migration and invasion of CD133+CD44+ CSCs in vitro." (PMID 33819194, 2021). "Moreover, we found that c-Myc, miR-200b-3p and PRDX2 expression levels were well associated with tumor differentiation, size and pathological Tumor-Node-Metastasis (pTNM) stage." (PMID 29258530, 2017). "We observed that PRDX2 expression was increased in tumor tissues of 6 out of 9 patients, with the highest expression in HCC cells and peritumoral cholangiocytes." (PMID 40932790, 2025). "Second, we assessed the effect of PRDX2 KO on tumor growth in a cell line–derived xenograft (CDX) mouse model." (PMID 40932790, 2025). "Prdx2 KO improved liver weight and decreased tumor burden, tumor size, and cell proliferation, as shown at macroscopic observations and by the decreased expression of the proliferation marker minichromosome maintenance complex component 2 (MCM2)." (PMID 40932790, 2025). "Across multiple in vivo and in vitro models, PRDX2 inhibition restores metabolic homeostasis, reduces tumor initiation, and selectively impairs HCC cell survival." (PMID 41422481, 2025). "SOX11KO or PRDX2 silencing significantly unbalance tumor redox homeostasis, becoming tumor cells very sensitive to chemotherapy due to the lethal levels of ROS produced in MCL cells." (PMID 38570586, 2024). "PRDX2 (Peroxiredoxin 2) plays an antioxidant protective role in cells and has been identified as a novel potential tumor suppressor gene in AML." (PMID 38650628, 2024). "In our study, the ccRCC-derived cell lines released variable amounts of PRDX2, despite consistently decreased mRNA expression in ccRCC cell lines and tumor tissues." (PMID 36604669, 2023). "In parallel, PRDX2 is the most efficient endogenous antioxidant compared with the other antioxidants which has both tumor suppressor and tumor promoting activities." (PMID 37501157, 2023). "Both PRDX1 and PRDX2 were upregulated in GBM compared to non-tumor brain tissues and their considerable amounts were observed in GBM cells." (PMID 37566013, 2023). "Results revealed that the expression level of PRDX2 in HCC tumor tissues was significantly higher than that in para-tumor tissues." (PMID 38188679, 2023). "This study shows the upregulation of PRDX1 and PRDX2 antioxidant enzymes in GBM compared to non-tumor brain tissues." (PMID 37566013, 2023).